MCM4 (minichromosome maintenance complex component 4)
Diseases named in the same sentence as MCM4 in open-access papers (continued):
Sharing a sentence is not in itself a finding about the gene and the disease.
Barrett esophagus (3 papers, 2015 to 2020). Esophageal lesion lined with columnar metaplastic epithelium which is flat or villiform. "Higher percentage of MCM4 expression also showed significantly worse prognosis in patients with esophageal adenocarcinoma and is associated with lymph node metaplasia, making MCM4 a better proliferative marker." (PMID 27476776, 2016). "Next, we investigated the clinicopathologic association of MCM4, MCM7, and Ki-67 expression in esophageal adenocarcinoma, squamous cell carcinoma, and precancerous lesions." (PMID 27476776, 2016). "High CA9 expression was significantly associated with MCM4, MCM7 and Ki67 expression in esophageal adenocarcinoma and precancerous lesions." (PMID 26156831, 2015). "This association may be related to significantly shorter survival in the esophageal adenocarcinoma group with high MCM4 expression level (>70%)." (PMID 27476776, 2016). "Finally, we analyzed the association of CA9 overexpression with BMI1, cyclin E, MCM4, MCM7 and Ki67 expression in esophageal adenocarcinoma." (PMID 26156831, 2015). "The mean percentages of MCM4 and MCM7 expression increased from squamous epithelium (6% and 7%) to columnar cell metaplasia (11% and 14%) and Barrett's esophagus (28% and 35%)." (PMID 27476776, 2016). "While MCM4 and MCM7 expression were located mainly at the base of glands in columnar cell metaplasia and Barrett's esophagus, their expression extended superficially to involve entire glands as the lesions progressed from dysplasia to adenocarcinoma." (PMID 27476776, 2016). "Bmi1 is a stem cell marker with similar distribution to those of MCM4, MCM7, and Ki-67 in esophageal adenocarcinoma and precancerous lesions." (PMID 27476776, 2016). "Kaplan– Meier survival curves to analyze the difference between high and low expression level for MCM4, MCM7, and Ki-67 were generated based on overall survival in patients with esophageal adenocarcinoma and those with squamous cell carcinoma." (PMID 27476776, 2016). "Our study investigated the correlation between MCM4 and MCM7 expression and Ki-67, Bmi1, and cyclin E expression in esophageal adenocarcinoma, squamous cell carcinoma, and precancerous lesions." (PMID 27476776, 2016). "Pairwise mean comparisons found the percentages of MCM4, MCM7, and Ki-67 expression in esophageal adenocarcinoma and high-grade dysplasia to be significantly greater than those in low-grade dysplasia, Barrett's esophagus, columnar cell metaplasia, and squamous epithelium (P < .05)." (PMID 27476776, 2016).
bladder cancer (3 papers, 2016 to 2024). "In addition, TACC3 is highly co-expressed with MCM4, CDC6, and CDC25A, indicated by correlation analysis using RNA-seq data of 42 bladder cancer clinical samples from our group published before." (PMID 29358577, 2018).
breast tumors (3 papers, 2016 to 2025). "The relative gene expression analysis of seven PGC-associated genes, including CCNB1, CCNB2, FEN1, MCM4, PTTG1, RACGAP1, and UBE2C, was conducted on the samples of breast tumors compared to healthy mammary tissues." (PMID 41009526, 2025). "Breast tumor stromal cells exhibit a distinct expression profile, marked by the expression of genes such as FEN1, RACGAP1, and MCM4, which may delineate their functional identity." (PMID 41009526, 2025).
colon cancer (3 papers, 2013 to 2020). "In fact, the expression level of E2F2 was very low level in colon cancer and E2F2 inhibition could enhance proliferation and cell cycle of colon cancer cells by suppressing the expression of surviving and regulating the expression of C-MYC, CCNA2, MCM4 as well as CDK2." (PMID 32117628, 2020).
esophageal squamous cell carcinoma (3 papers, 2016 to 2023). Esophageal squamous cell carcinoma (ESCC) is a type of esophageal carcinoma (EC) that can affect any part of the esophagus, but is usually located in the upper or middle third. "A previous study of MCM4 expression in esophageal squamous cell carcinoma found a significant association between increased expression and higher histologic stage." (PMID 27476776, 2016). "Via reverse-transcription polymerase chain reaction (RT-PCR), MCM4 expression was reported to be increased in esophageal squamous cell carcinoma when compared with normal epithelium." (PMID 27476776, 2016). "MCM4 mRNA expression has also been observed in esophageal squamous cell carcinoma." (PMID 27476776, 2016). "It has been reported that MCM4 and CENPI are involved in mediating chromosomal stability to influence the cell cycle and that KNTC1 knockdown suppresses cell viability and induces apoptosis in esophageal squamous cell carcinoma." (PMID 36035209, 2022).
liver cancer (3 papers, 2017 to 2021). An epithelial or non-epithelial malignant neoplasm that arises from the liver. "More than that, the results from HPA IHC data and western blot detection of 4 pairs of HCC patients' tissues identified MCM4 protein high expression level in the liver cancer group." (PMID 34961841, 2021). "In the MCM family, abnormal expression of MCM2, MCM3, MCM4, MCM5, and MCM7 also results in reducing prognosis in liver cancer patients according to the HCCDB database." (PMID 32082966, 2019).
sarcoma (3 papers, 2021). A usually aggressive malignant neoplasm of the soft tissue or bone. "Interestingly, the association of MCM4-high expression with genomic instability and BRCAness were not only validated in LPS samples from our institution (n = 66) but also could be expanded to the pan-sarcoma cohort from TCGA database (n = 263)." (PMID 34178990, 2021). "The results showed that high expression of MCM2, MCM3 and MCM4 was significantly related to poor OS of sarcoma patients." (PMID 34239894, 2021). "MCM2, and MCM4–7 were highly expressed in sarcoma in GEPIA database." (PMID 34239894, 2021). "Moreover, high levels of MCM2 and MCM4 mRNA significantly decreased the OS (p < 0.05) of sarcoma patients." (PMID 34239894, 2021). "So MCM2, MCM3, and MCM4 seemed to be three potential biomarkers for the prognosis of sarcoma." (PMID 34239894, 2021). "Using datasets of Barretina Sarcoma, compared with normal samples, MCM4 was overexpressed in pleomorphic liposarcoma, myxofibrosarcoma, dedifferentiated liposarcoma, leiomyosarcoma and myxoid/round cell liposarcoma, with the fold change of 3.142, 3.455, 2.195, 3.042, and 2.227 respectively." (PMID 34239894, 2021). "Surprisingly, based on four sarcoma cell lines and eight PTCCs (three LPS and five other sarcoma), we demonstrated that MCM4 overexpression tumors were therapeutically sensitive to PARP inhibitor (PARPi) and platinum chemotherapy, independent of the histology subtypes." (PMID 34178990, 2021). "Therefore, the prognostic role of MCM4 in sarcoma may be attributable to changes in DNA methylation patterns." (PMID 34239894, 2021). "Therefore, the mechanism of prognostic value of MCM4 in sarcoma was explored." (PMID 34239894, 2021). "We found that except for MCM1, all other MCM factors had higher expression levels in sarcoma than in normal tissues (p < 0.05 for MCM2, MCM4, MCM5, MCM6 and MCM7)." (PMID 34239894, 2021). "Furthermore, we analyzed the prognostic value of MCMs for sarcoma in GEPIA and found that MCM2, MCM3, MCM4, and MCM10 are prognostic biomarkers for human sarcoma." (PMID 34239894, 2021). "According to the results, we found that MCM2 and MCM4 were elevated expressed in ONCOMINE and GEPIA datasets with prognostic values, so the key MCM family genes including MCM2 and MCM4 were chosen to be confirmed in sarcoma cell lines." (PMID 34239894, 2021). "Therefore, MCM2, MCM3, MCM4, and MCM10 were four potential biomarkers for the prognosis of sarcoma and a higher expression indicates worse outcomes." (PMID 34239894, 2021).
uterine corpus endometrial carcinoma (3 papers, 2022 to 2025). A endometrial carcinoma (disease) that involves the body of uterus. "Given that MCM4 has been reported to be aberrantly expressed in a variety of tumor tissues, and is strongly associated with poor patient prognosis, it has rarely been reported in uterine corpus endometrial carcinoma (UCEC)." (PMID 35719366, 2022). "In uterine corpus endometrial carcinoma, MCM4 has been proposed as a novel prognostic biomarker based on its correlation with disease progression." (PMID 40564876, 2025).
viral diseases (3 papers, 2010 to 2023). "Isolated deficiencies of ILCs and NK cells in patients with IEIs, such as GINS1, MCM4, or MCM10 deficiency, can lead to various degrees of susceptibility to viral diseases, mostly caused by CMV." (PMID 36736301, 2023). "In some defects, such as deficiencies of MCM4, GINS1, and MCM10, where there is a significant susceptibility to recurrent and severe viral infections, the pathogenesis may be explained by severely defective NK cells." (PMID 36986362, 2023). "This difference between wild type and mutant virus infection was apparent for both MCM2 and MCM4, although the effect on MCM4 was greater." (PMID 20333247, 2010).
and glucocorticoid deficiency (2 papers, 2014 to 2022). "The TXNRD2 mutation in this family and the other recently described FGD syndromes due to mutations in NNT and MCM4 highlight important pathogenic pathways in addition to defective ACTH signaling, causing glucocorticoid deficiency." (PMID 24601690, 2014).
autoimmune disease (2 papers, 2022 to 2023). A disorder resulting from loss of function or tissue destruction of an organ or multiple organs, arising from humoral or cellular immune responses of the individual to their own tissue constituents. "Most genes were related to autoimmune diseases like ATM, NCF1, MCM4, FCN3, and DOCK8 or autoinflammatory diseases associated with the release of IFN-gamma, such as PRF1, NOD2, and MEF." (PMID 37588055, 2023).
Ewing sarcoma (2 papers, 2017 to 2025). A small round cell tumor that lacks morphologic, immunohistochemical, and electron microscopic evidence of neuroectodermal differentiation. "Further supporting a critical role for the MCM2–7 and the pre-RC in Ewing sarcoma tumors, the Dbf4-dependent Cdc7 kinase (DDK), which initiates replisome assembly by phosphorylating the N-terminal tails of Mcm2, Mcm4, and Mcm6, was recently identified as a target in Ewing sarcoma tumors." (PMID 40478628, 2025).
fibrosarcoma (2 papers, 2021). A malignant mesenchymal fibroblastic neoplasm affecting the soft tissue and bone. "A survey of all STS registries in Oncomine database confirmed a consistent overexpression of MCM4 not only in LPS but also in leiomyosarcoma, fibrosarcoma, synovial sarcoma, and undifferentiated pleomorphic sarcoma, compared with the normal." (PMID 34178990, 2021).
laryngeal squamous cell carcinoma (2 papers, 2018 to 2021). A squamous cell carcinoma that arises from the larynx. "Thus, the overexpression of MCM4 gene was detected in laryngeal squamous cell carcinoma and this gene was also implicated in other cancers because it codes for an important component of the DNA replication machinery." (PMID 29371888, 2018).
MIRAGE syndrome (2 papers, 2020 to 2023). An autosomal dominant condition caused by mutation(s) in the SAMD9 gene, encoding sterile alpha motif domain-containing protein 9A. "The syndromic category includes four different forms which are AAA syndrome (AAAS mutations), IMAGE syndrome (CDKN1C mutations), MIRAGE syndrome (SAMD9 mutations), and a syndrome with MCM4 mutations." (PMID 31208161, 2020).
serous ovarian cancer (2 papers, 2019 to 2021). "The serous ovarian cancer dataset indicated that the percentages of DNA alterations of MCMs were 5% (MCM2), 4% (MCM3), 5% (MCM4), 2.6% (MCM5), 1.2% (MCM6), and 5% (MCM7)." (PMID 34178669, 2021).
squamous cell carcinoma (2 papers, 2015 to 2016). A carcinoma arising from squamous epithelial cells. "The mean percentages of MCM4 and MCM7 expression were also high in squamous cell carcinoma (74% and 85%)." (PMID 27476776, 2016). "Additionally, the percentages of MCM4, MCM7, and Ki-67 expression in squamous cell carcinoma were significantly greater than those in squamous epithelium." (PMID 27476776, 2016). "Correlations between MCM4, MCM7, and Ki-67 expression and patients' clinicopathologic characteristics, including age, gender, TNM stage, and histologic grade, were analyzed in the adenocarcinoma group and the squamous cell carcinoma group." (PMID 27476776, 2016). "However, the overall survival time between high (mean, 34.8 months) and low (mean, 48.5 months) expression levels for MCM4 lacked significance in the squamous cell carcinoma group." (PMID 27476776, 2016).
adenoma (1 paper, 2020). A neoplasm arising from the epithelium. "Unbiased analysis of the MYC targets V2 gene set revealed clusters correlated with the tumor histopathology, and adenocarcinoma-derived PDOs exhibited the high expression of distinct genes from adenoma-derived PDOs related to cellular proliferation, including CDK4, PLK1 and 4, MCM4, and MYC." (PMID 33060766, 2020).
anemia (1 paper, 2019). A reduction in the number of red blood cells, the amount of hemoglobin, and/or the volume of packed red blood cells. "We examined global transcriptome alterations following depletion of DNA replication checkpoint genes (Atr, Mcm4, Mcm5, and Mcm6), the Fanconi anemia gene (Fanca), mRNA processing genes (Snrpal and Snrpd3), and CMT genes (Sh3tc2 and Cmt4b2)." (PMID 31390555, 2019).
diabetes (1 paper, 2017). "Therefore, a functional role of MCM4 gene was presented in the context of vascular injury commonly found in diabetes." (PMID 28812028, 2017).
dissection (1 paper, 2021). The separation and isolation of tissues for surgical purposes, or for the analysis or study of their structures. "In summary, our studies showed that MCM2, MCM4, and MCM10 play an important role in aortic dissection and the expression of MCMs was inhibited by atorvastatin treatment." (PMID 33803192, 2021).
esophageal diseases (1 paper, 2016). "The significant increase of MCM4 and MCM7 expression compared with Ki-67 suggests that MCM4 and MCM7 are potentially more sensitive markers in differentiating various stages of esophageal disease progression." (PMID 27476776, 2016).
gastroesophageal reflux disease (1 paper, 2015). A chronic disorder characterized by reflux of the gastric and/or duodenal contents into the distal esophagus. "High CA9 expression may be related to the acidic environment caused by gastroesophageal reflux disease in the gastroesophageal junction and associated with tumorigenesis through BMI1, MCM4 and MCM7." (PMID 26156831, 2015).
HCMV infection (1 paper, 2010). "The altered accumulation of MCM proteins was likely to occur at a post-transcriptional level as MCM4 transcript accumulated at similar levels during HCMV infection independent of pUL117." (PMID 20333247, 2010). "We have also observed MCM4 hyper-phosphorylation at late times during mutant and wild type HCMV infection (data not shown)." (PMID 20333247, 2010).
head and neck cancer (1 paper, 2025). A primary or metastatic malignant neoplasm affecting the head and neck. "MCM6 showed similar correlations, except in HPV+ head and neck cancer, while MCM4 was positively correlated with C1GALT1 across all cancer types." (PMID 40548474, 2025).
hepatitis B infection (1 paper, 2019). "The survival analysis from another dataset, GSE14520, supported our results, which showed that MCM4 enrichment had significant association with the OS in HCC patients in the background of hepatitis B infection." (PMID 31695969, 2019).
Intellectual disability (1 paper, 2019). "Interestingly, the patient exhibited intellectual disability, severe intrauterine growth delay, and postnatal growth retardation, as well as multiple serious infections, features resembling MCM4 deficiency." (PMID 31672938, 2019).
large-cell lung carcinoma (1 paper, 2021). "In Hou’s dataset, MCM4 was overexpressed in all of the NSCLC subtypes: in LUAD with a fold change of 3.39, in large-cell lung carcinoma with a fold change of 4.908, and in LUSC with a fold change of 5.794." (PMID 33936158, 2021).
lipoma (1 paper, 2021). A benign, usually painless, well-circumscribed lipomatous tumor composed of adipose tissue. "Next, we performed IHC staining of MCM4 for 66 archived surgical specimens in our institution, including 39 LPS, 22 lipomas, and 5 normal adipose tissues." (PMID 34178990, 2021).
liposarcoma (1 paper, 2021). A usually painless malignant tumor that arises from adipose tissue. "Correlation between MCM4 expression and pathological parameters in liposarcoma (LPS)." (PMID 34178990, 2021).
lymphopenia (1 paper, 2018). Reduction in the number of lymphocytes. "Interestingly, patients with deficiencies in Mcm4 and Gins1, which are involved in DNA helicase complexes, have a profound NK cell lymphopenia." (PMID 29868001, 2018).
Lynch syndrome (1 paper, 2013). An autosomal dominant hereditary neoplastic syndrome characterized by the development of colorectal carcinoma and a high risk of developing endometrial carcinoma, gastric carcinoma, ovarian carcinoma, renal pelvis carcinoma, and small intestinal carcinoma. "Lynch syndrome tumors showed up-regulation of 1129 genes, e.g. genes involved in G1/S transition (CCNE, CCNH, E2F2 and CDK2), DNA replication (CDC45, RPA1, RFC5, MCM4 and POLD3) and chromosomal organization and mitosis (CCNB2, MLF1IP, CASC5, KIF2C and PLK4), which is in line with previous findings." (PMID 23951239, 2013).
metastasis (1 paper, 2022). The spread or migration of cancer cells from one part of the body (where they first appeared) to another. "Univariate and multivariate regression analyses demonstrated that higher expression of LINC00460 and MCM4 was significantly associated with tumor size, lymph node metastasis, distant metastasis and TNM stage." (PMID 36291859, 2022).
metastatic tumors (1 paper, 2025). "In the TCGA-SKCM cohort, metastatic tumors exhibited higher MCM4 expression compared to primary tumors." (PMID 40959096, 2025).
neuroblastoma (1 paper, 2023). Neuroblastoma (NB) is the most common solid, extracranial childhood tumor. "From our final list of 104 genes, 3 of them (MCM4, MCM7, and TERT) have already been found to be deregulated for their expression in high-risk neuroblastoma, but the great majority (101 genes) have not." (PMID 37759629, 2023).
primary immunodeficiency (1 paper, 2016). "We report a novel primary immunodeficiency, and a differential molecular diagnosis to CXCR4‐,DOCK8‐,GATA2‐,MAGT1‐,MCM4‐,STK4‐,RHOH‐,TMC6‐, and TMC8‐related diseases." (PMID 27896283, 2016).
rectal adenocarcinoma (1 paper, 2020). "The MCM4 was 1.690- and 2.030-fold as high as the normal tissues in colon and rectal adenocarcinoma samples, respectively." (PMID 32597491, 2020).
sensorineural hearing loss (1 paper, 2021). "The role of MCM proteins in cilia formation is also consistent with familial sensorineural hearing loss with MCM2 defects and adrenal disease in MCM4 NKD patients." (PMID 33477564, 2021).
tongue cancer (1 paper, 2021). A malignant neoplasm affecting the tongue.
triple-negative breast carcinoma (1 paper, 2022). An invasive breast carcinoma which is negative for expression of estrogen receptor (ER), progesterone receptor (PR), and human epidermal growth factor receptor 2 (HER2). "Overexpression of MCM2, MCM3, MCM4, and MCM6 is associated with luminal B, HER2+, and triple-negative breast cancers." (PMID 35401937, 2022).
upper tract urothelial carcinoma (1 paper, 2023). "We analyzed the expression and distribution of MCM4 in 124 upper tract urothelial carcinoma (UTUC) samples by IHC." (PMID 37737200, 2023).